YBX1 (Y-box binding protein 1)
Description:
DNA- and RNA-binding protein involved in various processes, such as translational repression, RNA stabilization, mRNA splicing, DNA repair and transcription regulation. Predominantly acts as a RNA-binding protein: binds preferentially to the 5'-[CU]CUGCG-3' RNA motif and specifically recognizes mRNA transcripts modified by C5-methylcytosine (m5C). Promotes mRNA stabilization: acts by binding to m5C-containing mRNAs and recruiting the mRNA stability maintainer ELAVL1, thereby preventing mRNA decay. Component of the CRD-mediated complex that promotes MYC mRNA stability. Contributes to the regulation of translation by modulating the interaction between the mRNA and eukaryotic initiation factors (By similarity). Plays a key role in RNA composition of extracellular exosomes by defining the sorting of small non-coding RNAs, such as tRNAs, Y RNAs, Vault RNAs and miRNAs. Probably sorts RNAs in exosomes by recognizing and binding C5-methylcytosine (m5C)-containing RNAs. Acts as a key effector of epidermal progenitors by preventing epidermal progenitor senescence: acts by regulating the translation of a senescence-associated subset of cytokine mRNAs, possibly by binding to m5C-containing mRNAs. Also involved in pre-mRNA alternative splicing regulation: binds to splice sites in pre-mRNA and regulates splice site selection. Binds to TSC22D1 transcripts, thereby inhibiting their translation and negatively regulating TGF-beta-mediated transcription of COL1A2 (By similarity). Also able to bind DNA: regulates transcription of the multidrug resistance gene MDR1 is enhanced in presence of the APEX1 acetylated form at 'Lys-6' and 'Lys-7'. Binds to promoters that contain a Y-box (5'-CTGATTGGCCAA-3'), such as MDR1 and HLA class II genes. Promotes separation of DNA strands that contain mismatches or are modified by cisplatin. Has endonucleolytic activity and can introduce nicks or breaks into double-stranded DNA, suggesting a role in DNA repair. The secreted form acts as an extracellular mitogen and stimulates cell migration and proliferation.
Synonyms: YB-1; CBF-A; DBPB; EFI-A; NSEP1; YB1; NSEP-1; MDR-NF1; BP-8; CSDB; CSDA2
Tractability: Antibody: UniProt places it where antibodies can reach, with high confidence; its Gene Ontology location is reachable by antibodies, with high confidence. PROTAC: UniProt records ubiquitination sites on it; ubiquitination databases record sites on it; its protein half-life has been measured.
Target class: Transcription factor
Gene: Protein-coding gene on chromosome 1 (42,682,408 to 42,703,805, forward strand). Ensembl gene ENSG00000065978.
Subcellular location: Cytoplasm; Nucleus; Cytoplasmic granule; Secreted; Secreted, extracellular exosome; Cytoplasm, P-body
Subcellular location (Human Protein Atlas): Cytosol; Endoplasmic reticulum; Plasma membrane; Vesicles
Pathways (Reactome):
Metabolism of RNA: Processing of Capped Intron-Containing Pre-mRNA; mRNA Polyadenylation; mRNA Splicing - Major Pathway; mRNA Splicing - Minor Pathway
Disease: Assembly and Release of Dengue Virus Virions; Dengue Virus Genome Translation and Replication; Dengue Virus-Host Interactions
Signal Transduction: Noncanonical activation of NOTCH3; SMAD2/SMAD3:SMAD4 heterotrimer regulates transcription
Immune System: Interferon gamma signaling
Gene Ontology:
Molecular function: C5-methylcytidine-containing RNA reader activity; GTPase binding; miRNA binding; protein binding; RNA binding; sequence-specific double-stranded DNA binding; DNA binding; double-stranded DNA binding; nucleic acid binding; chromatin binding; mRNA binding; single-stranded DNA binding
Biological process: CRD-mediated mRNA stabilization; miRNA transport; mRNA stabilization; negative regulation of nuclear-transcribed mRNA catabolic process, deadenylation-dependent decay; positive regulation of cytoplasmic translation; positive regulation of transcription by RNA polymerase II; protein localization to cytoplasmic stress granule; regulation of DNA-templated transcription; RNA transport; tRNA transport; embryonic morphogenesis; epidermis development; negative regulation of cellular senescence; negative regulation of translation; regulation of gene expression
Cellular component: CRD-mediated mRNA stability complex; cytoplasm; cytoplasmic stress granule; cytosol; extracellular exosome; extracellular region; nucleus; ribonucleoprotein complex; U12-type spliceosomal complex; histone pre-mRNA 3'end processing complex; nucleoplasm; P-body; synapse
Genetic constraint (gnomAD): Loss-of-function variants: 3 observed, 38.88 expected, observed/expected ratio (o/e) 0.0772, 90% interval 0.034 to 0.2. The upper end of that interval is the gene's LOEUF score, 0.2, which puts it in group 1 of 6, group 1 being the genes least tolerant of losing a copy. Missense variants: 274 observed, 416.03 expected, observed/expected ratio (o/e) 0.66, 90% interval 0.6 to 0.73. Synonymous variants: 133 observed, 138.29 expected, observed/expected ratio (o/e) 0.96, 90% interval 0.83 to 1.11.
Homologues: Orthologues: macaque YBX1 (100% identical), pig YBX1 (99% identical), mouse Ybx1 (98% identical), rat Ybx1 (98% identical), rat Ybx1l1 (94% identical), tropical clawed frog ybx1 (80% identical), zebrafish ybx1 (70% identical), Caenorhabditis elegans cey-4 (31% identical), Caenorhabditis elegans cey-2 (26% identical), Caenorhabditis elegans cey-3 (25% identical), Drosophila melanogaster lin-28 (17% identical). Paralogues in human: YBX3 (63% identical), YBX2 (49% identical), LIN28B (26% identical), LIN28A (23% identical).
Diseases named in the same sentence as YBX1 in open-access papers:
YBX1 is named in the same sentence as 243 diseases in open-access papers, as found by Europe PMC text mining. Sharing a sentence is not in itself a finding about the gene and the disease. The quoted sentences say what the papers report.
breast carcinoma (243 papers, 2007 to 2026). "Other common upregulated transcription factor activity includes YBX1, associated with aggressiveness in breast cancer, and ZBTB33 (also known as Kaiso) which had been associated with metastatic activity in MDA-MB-231 cells." (PMID 38184712, 2024). "The Kaplan–Meier survival analysis showed a significant association between elevated expressions of KMT2D and YBX1 and poor survival of breast cancer patients within this cohort." (PMID 38967349, 2024). "In 1997, YBX1 was implicated in the progression of breast cancer, and in 1998, its involvement in osteosarcoma was reported." (PMID 39727969, 2024). "A prooncogenic role for YBX1 is suggested by previous studies that the increased expression of YBX1 is associated with cancer aggressiveness in various cancers, including breast carcinoma, colorectal cancer sarcoma and intrahepatic cholangiocarcinoma." (PMID 38698857, 2024). "YBX1's high expression in breast cancer is associated with low survival, drug resistance, and high recurrence rates for all subtypes, indicating the potential importance of YBX1 as an oncogene in breast cancer." (PMID 37170222, 2023). "High YBX1 levels have been associated with poor prognosis of breast cancer patients and relapse following surgical resection." (PMID 35721477, 2022). "For example, the untranslated region (UTR) of the TRF binding protein YBX1 can inhibit the growth of cancer cells caused by serum starvation, cancer cell invasion, and breast cancer metastasis." (PMID 35281615, 2022). "Examination of three large breast cancer datasets show that elevated levels of YBX1 (hereafter referred to as YB-1) transcripts are associated with a reduced overall survival of patients with ER- breast cancers, most notably in those with metastatic disease." (PMID 34294889, 2022). "We further performed a gene set enrichment analysis (GSEA), and results showed that YBX1 overexpression was positively associated with the glycolysis hallmark using GEO breast cancer cohorts." (PMID 34440660, 2021). "Bipotent stem-cell-like cells are associated with the clinical outcome of breast cancer, that is, overexpression of regulatory genes Ybx1 and ENO1 is associated with the risk of breast cancer." (PMID 33614479, 2020). "YBX1 is a well-known oncoprotein linked to cancer progression, including breast cancer, hepatocellular carcinoma, gastrointestinal cancer and prostate cancer." (PMID 32165621, 2020). "The bipotent stem-like state correlates with clinical outcome in basal breast cancer and is characterized by overexpression of YBX1 and ENO1, two modulators of basal breast cancer risk." (PMID 31428694, 2019). "Y-box binding protein 1 (YBX1) is one such molecular target that has been implicated in numerous human malignancies including breast cancer, prostate cancer, nasopharyngeal carcinoma, lung adenocarcinoma, and sarcoma." (PMID 31481087, 2019). "We next examined the association between YBX1 and the genes correlated with YBX1 in 13 breast cancer cell lines established from HR+/HER2-, HR-/HER2+, and HR-/HER2- tumors." (PMID 30647855, 2018). "We further examined the association between YBX1-correlated genes and breast cancer outcomes in patients at Kyushu University Hospital." (PMID 30647855, 2018). "Recently, emerging studies have indicated that dysregulation of YBX1 is linked to tumor progression, including prostate cancer, breast cancer, and bladder cancer." (PMID 29029484, 2017). "Almost all these elements in the cascade were associated with breast cancer except YBX1 and miR-181c." (PMID 25932650, 2015). "It has been previously demonstrated that the phosphatidylinositide 3-kinase [PI3K/AKT] pathway causes the phosphorylation of S102 on YBX1 protein and governs its nuclear translocation in breast cancer cells." (PMID 26318844, 2015).
breast carcinoma (continued). "Studies have shown that overexpression of YBX1 is associated with various tumor types’ resistance to therapy, cell proliferation, and prognosis, such as breast cancer, esophageal cancer, lung cancer, sarcomas, prostate cancer, glioblastoma, and non-Hodgkin lymphoma." (PMID 39497723, 2024). "Additionally, another study found that high expression of YBX1 in ER+ breast cancer patients was associated with poor prognosis." (PMID 31355251, 2019). "Consistent with this notion, we explored whether YBX1 and the genes closely correlated with YBX1 were associated with breast cancer recurrence." (PMID 30647855, 2018). "Mutation of the S102 site of YBX1 inhibited tumor growth via the Akt/PKB pathway in breast cancer." (PMID 26318844, 2015). "Recently, a number of studies showed that the over-expression of P-gp appears to be closely associated with the nuclear localization of Y-box binding protein 1(YB-1) in various solid tumors such as breast cancer, ovarian cancer, prostate cancer, and osteosarcoma." (PMID 23967153, 2013). "Moreover, YBX1 expression was positively associated with epithelial-to-mesenchymal transition (EMT) genes in breast cancer patients, and suppression of YBX1 downregulated expressions of EMT-related genes and tumor migration and invasion in MDA-MB-231 and BT549 TNBC cells." (PMID 34440660, 2021). "Determining the expression levels of YBX1 and its correlated genes can therefore aid in the identification of patients with a high risk of recurrence, and YBX1 and its correlated genes may be useful biomarkers for the precise prediction of breast cancer patients with a high risk of recurrence." (PMID 30647855, 2018). "YBX1 induces increased expression of MMP14 in breast cancer, and overexpression of YBX1 leads to more locally invasive, lung metastatic and highly lethal breast cancer cells." (PMID 41507135, 2026). "Serum YBX1 can be used as a molecular marker in patients with bone metastases from breast cancer, and serum YBX1-positive patients also have higher expression of IL-6, a known osteogenesis-inducing molecule." (PMID 41507135, 2026). "AATBC activates YAP1/Hippo signaling pathway by interacting with YBX1, promoting breast cancer migration and invasion." (PMID 40799245, 2025). "To confirm the interaction between CD2BP2‐DT and YBX1 in breast cancer cells, we conducted biotin‐labeled RNA pull‐down and RNA immunoprecipitation (RIP) assays." (PMID 39976088, 2025). "In breast cancer, YBX1 and the transcription factor NFIB bind to estrogen receptors and regulate the proliferation, growth, metastasis, and response to hormone therapy of tumor cells through the FGFR2 signaling pathway." (PMID 40799245, 2025). "A specific group of tRFs functionally binds to the oncogenic RNA-binding protein YBX1, displacing YBX1 from its target transcripts and suppressing breast cancer progression." (PMID 40153423, 2025). "When YBX1 was overexpressed in breast cancer cells with stable CD2BP2‐DT knockdown, the proliferation inhibition caused by CD2BP2‐DT knockdown was partially reversed." (PMID 39976088, 2025). "Fluorescence imaging revealed that overexpression of CD2BP2‐DT significantly enhanced the formation of YBX1 droplets, while knockdown of CD2BP2‐DT markedly inhibited YBX1 droplet formation in breast cancer cells." (PMID 39976088, 2025). "Endogenous tRF identified from breast cancer plays a regulatory role through the RNAi pathway to target YBX1, resulting in suppressing breast cancer." (PMID 39736854, 2025). "TAS0612 and everolimus target YBX1 phosphorylation, addressing anti-estrogen treatment resistance in advanced breast cancer." (PMID 40799245, 2025). "In conclusion, the lncRNA CD2BP2‐DT is identified as a crucial driver of breast cancer cell proliferation through the YBX1/CDK1 axis, highlighting its potential as a promising biomarker and therapeutic target for breast cancer." (PMID 39976088, 2025).
breast carcinoma (continued). "Due to its numerous cellular functions, YBX1 has been demonstrated to be involved in various human malignancies, including pancreatic cancer, breast cancer, lung cancer, multiple myeloma, osteosarcoma, synovial sarcoma, prostate cancer, and ovarian cancer." (PMID 40593465, 2025). "AC073352.1 lncRNA promotes breast cancer metastasis by stabilizing YBX1 protein and promoting angiogenesis." (PMID 40799245, 2025). "Further observations revealed that YBX1 liquid droplets exhibited fusion behavior in breast cancer cells." (PMID 39976088, 2025). "In breast cancer, a class of endogenous tRNA fragments has been found to displace the 3’UTR of target mRNA from the RNA-binding protein YBX1, thereby inhibiting the stability of multiple oncogenic transcripts in breast cancer cells." (PMID 40855047, 2025). "More importantly, CD2BP2‐DT enhances the stability of CDK1 mRNA by mediating YBX1 phase separation, thereby promoting the proliferation of breast cancer cells." (PMID 39976088, 2025). "JMJD6 inhibitor has been used to regress tumours in preclinical mouse models and several efforts are being made to design YBX1 inhibitors since it promotes breast cancer metastasis." (PMID 40855961, 2025). "Lastly, in breast cancer, YBX1 gene silencing reduces the expression of CORO1C gene and inhibits the migration and invasion potential of breast cancer cells." (PMID 40799245, 2025). "Previous studies have shown that the expression of YBX1 is upregulated in many cancers, including breast cancer, gastric cancer, and hepatocellular carcinoma." (PMID 38849679, 2024). "Increased YBX1 expression in breast cancer suppresses cell proliferation by impeding the translation of growth-related mRNAs and concurrently enhancing mesenchymal gene expression, promoting cell survival in anchorage-independent conditions." (PMID 38255791, 2024). "Oncogenic AURKA influences breast cancer-related RNA splicing, interacting with YBX1 to promote GOLGA4 exon inclusion and with hnRNPK to induce RBM4 exon skipping." (PMID 38255791, 2024). "In order to assess the clinical significance of KMT2D and YBX1 in breast cancer, we used a tissue microarray containing 140 breast cancer tissues and 77 adjacent healthy tissues." (PMID 38967349, 2024). "The use of AAV vectors to knockdown KMT2D and YBX1 in the mammary glands of MMTV‐PyMT transgenic (MMTV‐KMT2D‐KD or MMTV‐YBX1‐KD) mice enabled us to test their therapeutic potential in breast cancer." (PMID 38967349, 2024). "In stable YBX1 knockdown breast cancer cells, there was a substantial decrease in both mRNA and protein levels of matrix metalloproteinase-1 (MMP-1) and beta-catenin." (PMID 38255791, 2024). "Among these proteins, YBX1 was found to be most highly expressed in the TNBC subtype of breast cancer, and highly expressed YBX1 significantly affected the OS and RFS survival probabilities of breast cancer patients." (PMID 39073262, 2024). "For example, hsa_circ_0007990 inhibits YBX1 protein to promote breast cancer growth, while CircPCNXL2 is reported to promote cholangiocarcinoma metastasis by interacting with STRAP." (PMID 39581695, 2024). "For example, 2,4-dihydroxy-5-pyrimidinyl imidothiocarbamate (DPI) inhibits the malignant phenotype of breast cancer by preventing YBX1’s nuclear translocation and the activation of its downstream target genes." (PMID 39727969, 2024). "Collectively, these findings suggest that knockdown of KMT2D and YBX1 impairs breast cancer growth and metastasis." (PMID 38967349, 2024). "TAS0612 elicits the inhibition effect on AKT, p70S6K, and p90RSK and thereby inhibits YBX1 phosphorylation and reverse antiestrogen resistance in breast cancer." (PMID 38255791, 2024). "For instance, in breast cancer with bone metastases, serum levels of secreted YBX1 (sYBX1) were found to correlate with extra-bone metastases and faster bone disease progression." (PMID 38255791, 2024).